CDX2 (caudal type homeobox 2)
Diseases named in the same sentence as CDX2 in open-access papers (continued):
Sharing a sentence is not in itself a finding about the gene and the disease.
gastric tumor (18 papers, 2012 to 2026). "CDX2 is normally a marker of intestinal epithelial identity; its expression in gastric tumors is generally associated with the intestinal histologic subtype and the presence of intestinal metaplasia in surrounding mucosa." (PMID 40862793, 2025). "However, loss of CDX2 enhances the invasive potential of gastric tumor cells." (PMID 37602699, 2023). "As expected, in line with another study on gastric neoplasms, CLDN18 was negatively associated with CDX2 expression in SBAs also." (PMID 35925388, 2022). "Additionally, these gastric tumor cells often exhibit positivity for CDX2, a marker indicative of gastrointestinal origin." (PMID 40893790, 2025). "In contrast, Cdx2 is essential for intestinal epithelium differentiation to regulate the expression of Muc2 and Tff3, and it is upregulated during the progression of gastric tumors." (PMID 26839577, 2016). "Immunohistochemically, the gastric tumor cells were positive for CK7, showed very focal CK20, with focal and weak SATB2, and diffuse CDX2 expression, consistent with primary gastric adenocarcinoma." (PMID 41159019, 2025). "The immunohistochemistry results for the gastric tumor were consistent with the lung tumor, also showing positivity for TTF-1, Napsin-A, and CK7, and negativity for CDX2 and CK20." (PMID 39465837, 2024). "CDX2 expression correlated with the severity of inflammation in non-malignant gastric cardia patients (p=0.023, chi-square)." (PMID 27384681, 2016). "The expression of CDX2 paralleled the severity of H. pylori infection from normal to severe infection in non-malignant gastric cardia and GCC patient cohort." (PMID 27384681, 2016). "SOX2, CDX2, MUC5AC and MUC2 expression were assessed in 201 gastric tumors by immunohistochemistry." (PMID 25300947, 2014).
neuroendocrine tumors (18 papers, 2012 to 2025). "Two early immunohistochemical surveys reported that CDX2 expression is highly sensitive and fairly specific for neuroendocrine tumors of midgut origin (jejunoileum or appendix)." (PMID 32245475, 2020). "CDX2 is also expressed in neuroendocrine tumors of the GI tract." (PMID 33504059, 2021). "In few studies the utility of markers indicating the origin of neuroendocrine tumors, such as cytokeratin CK20, CK7, thyroid transcription factor (TTF-1) and CDX-2 in ovarian neuroendocrine tumors were determined." (PMID 34917031, 2021). "The expression of CDX2 and PDX1 is highly specific for identifying neuroendocrine tumors of intestinal origin, since bronchopulmonary carcinoids seem to be negative for these two markers." (PMID 22269186, 2012). "This case corroborates earlier findings that cytokeratin 7 and pancytokeratin are often positive, while markers such as CDX2 and synaptophysin are negative, helping exclude adenocarcinoma and neuroendocrine tumors, respectively." (PMID 39860304, 2025). "Thyroid transcription factor 1 (TTF-1), a marker for metastases in NETs of pulmonary origin, and CDX2, a marker for metastases of gastrointestinal origin, were mostly negative in presacral neuroendocrine tumors." (PMID 34690926, 2021). "Unlike the NKX2.2, PDX-1, and CDX-2 that had restricted expression pattern in NETs of different site, PTF1A was expressed in all normal and neuroendocrine tumor cells (data not shown)." (PMID 29713473, 2018).
ovarian carcinoma (18 papers, 2007 to 2025). A malignant neoplasm originating from the surface ovarian epithelium. "A total of 4,107 cases and 6,661 controls from 11 subgroup studies that reported the association between the 5 common variants (ApaI, BsmI, Cdx-2, FokI and TaqI) and ovarian cancer risk were included in the meta-analysis." (PMID 23826116, 2013). "In the current study, we evaluated, in a meta-analysis, the association of five common single nucleotide polymorphisms (SNPs) in the VDR gene (ApaI, BsmI, Cdx-2, FokI, and TaqI) with the risk of ovarian cancer." (PMID 23826116, 2013). "Two reports with 4 subgroup studies and with a total of 1,567 cases and 2,226 controls evaluated the association of Cdx-2 and ovarian cancer risk." (PMID 23826116, 2013). "The present meta-analysis evaluated the association of five common VDR polymorphisms (ApaI, BsmI, Cdx-2, FokI and TaqI) and the risk of ovarian cancer." (PMID 23826116, 2013). "Associations between VDR polymorphisms (ApaI, BsmI, Cdx-2, FokI, TaqI) and the risk of ovarian cancer under different genetic models." (PMID 23826116, 2013). "These immunohistochemical findings indicate that endogenous MDR1 expression is associated with CDX2 expression in human ovarian cancer tissue as well as mucinous ovarian cancer tissues (P < 0.001; in human ovarian cancer, and P < 0.05; in mucinous ovarian cancer, using Fisher's exact test)." (PMID 27060927, 2016). "In another ovarian cancer study, immunohistochemical staining showed that only 15.1% (8/53) of tissues show CDX2 expression and CDX2 was found to contribute to chemoresistance via the promotion of MDR1 (multidrug resistance 1) gene expression." (PMID 40002854, 2025). "Of 53 ovarian cancer cases studied, eight cases displayed positive CDX2 expression (15.1%) and 21 displayed positive MDR1 expression (39.6%)." (PMID 27060927, 2016). "However, since CDX2 loss could contribute to aggressive tumor behavior considering the roles of CDX2 in promoting cellular differentiation and inhibiting proliferation 13, it remains unclear whether CDX2 loss plays a critical role in ovarian cancer progression." (PMID 27060927, 2016). "In one study, the Cdx-2 polymorphism was associated with an increased risk of developing ovarian cancer in Japanese women but not in other ethnic groups." (PMID 32024052, 2020). "However, in several recent published papers, CDX2 was found to be aberrantly expressed in gastric, thyroid and ovarian cancer." (PMID 27384681, 2016). "On the basis of an evaluation of clinical tissues of ovarian cancer cases, we observed overexpression of CDX2 in ovarian mucinous adenocarcinoma but only weak expression in other histological types, including serous adenocarcinoma, endometrioid adenocarcinoma, and clear cell carcinoma." (PMID 27060927, 2016). "Interestingly, Cdx2 and E47, known to be upregulated in ovarian carcinoma or PCOS ovaries, were repressed in the ovary at 120 min by PRL/PRL-RS signaling." (PMID 19703295, 2009). "The left ovary contained an intestinal-type tumor in which it was impossible to differentiate between an intestinal tract metastasis or primary ovarian cancer (intestinal-type), with immunohistochemical markers showing the expression of CK20 and CDX2." (PMID 40361393, 2025). "In ovarian cancer cells, REG4 expression or 5-FU chemoresistance was enhanced by CDX2 transfection, in contrast to CDX2 knockdown." (PMID 36172286, 2022). "There were two downregulated transcription factors (BARX2 and CDX2), a glutathione regulating enzyme (GGT6) and a serine protease that correlates with improved survival in ovarian cancer (PRSS16)." (PMID 31052165, 2019). "Additionally, primary ovarian carcinomas may exhibit variable positivity for keratin 20, CEA, and CDX2." (PMID 41517393, 2025). "CDX-2 is highly expressed in gallbladder cancer, while it is negative in primary ovarian cancer." (PMID 37420244, 2023). "Ovarian carcinoma binds antigens for CK7, CA125, ER, and is negative for CDX2, CK20, and TTF1." (PMID 18036260, 2007).
lymph node metastasis (17 papers, 2012 to 2024). "Patients with CDX2 loss had less often lung metastases and liver-only disease, but more often distant lymph node metastases." (PMID 32117703, 2020). "The present results indicate that Cdx2 overexpression, as detected by immunohistochemistry, were significantly associated with sex, clinical stage, differentiation, vascular invasion and lymph node metastasis, as well as 5-year survival rate." (PMID 23181722, 2012). "Reduced CDX2 was associated with lymph node metastasis (p = 0.0167), distant metastasis (p = 0.0123), and unfavorable survival (multivariate analysis: p = 0.0008; HR (95%CI) 0.922 (0.988–0.997)) as well as BRAFV600E, mismatch repair deficiency, and CpG island methylator phenotype." (PMID 30257705, 2018). "Loss of Cdx2 in lymph node metastasis was marginally associated with overall survival (p = 0.0512)." (PMID 24130965, 2013). "The prognostic and predictive value of CDX2 expression on the presence of lymph node metastasis (LNM) and survival was investigated." (PMID 30511046, 2018). "To further detect the correlation between CDX2 expression and lymph node metastasis, we divided the GCC patients into several subgroups, based on the site and number of metastatic lymphatic nodes." (PMID 27384681, 2016). "The protein expression of CDX2 was also markedly lower in the lymph node metastasis group than in the non-lymph node metastasis group." (PMID 26005051, 2015). "To this end, we had 11 cases available with peripancreatic lymph node metastasis, of which 4 (36.4%) were positive for CDX2 expression." (PMID 24489794, 2014). "According to multivariate analysis, only lymph node metastasis, TNM stage, and CDX2 expression were independently associated with survival." (PMID 24228025, 2013). "Based on the Cox regression analysis of the 172 patients, CDX2 expression, lymph node metastasis, and TNM stage seemed to be independent prognostic indicators (P = .026.011, and .001, resp.)." (PMID 24228025, 2013). "We also observed a correlation of Cdx2 positivity with lower (I+II) clinical stage, better histologic differentiation, and lower rate of vascular invasion and lymph node metastasis." (PMID 23181722, 2012). "Increased Cdx2 expression was correlated with a lower proportion of vascular invasion and lymph node metastasis." (PMID 23181722, 2012). "Of these, 59 patients had available lymph node metastases that underwent Cdx2 staining as well." (PMID 24130965, 2013). "The expression of CDX2 mRNA was significantly correlated with Lauren classification, TNM stage and lymph node metastasis." (PMID 23408490, 2013). "The expression of CDX2 mRNA was significantly correlated with Lauren classification, TNM stage and lymph node metastasis (all P<0.05)." (PMID 23408490, 2013). "The expression of CDX2 mRNA was correlated significantly with Lauren classification, TNM stage and lymph node metastasis." (PMID 23408490, 2013). "Several factors have been identified as potentially influencing prognosis, including smoking history, Eastern Cooperative Oncology Group (ECOG) performance status, tumor size ≤ 5 cm, lymph node metastasis, and expressions of biomarkers such as CK20, CDX-2, and NapsinA." (PMID 39507527, 2024). "CDX2 expression rates were not significantly different according to sex, tumor location, histologic grade, pT stage, lymph node metastasis, venous, lymphatic, perineural invasion, and pTNM stage in the meta-regression test." (PMID 35328309, 2022). "The results showed that Cdx2-positive expression had a significant correlation with clinical stage and lymph node metastasis (data not shown)." (PMID 23181722, 2012). "In addition to this, a negative correlation can be shown between the expression of CDX2 and TNM staging, lymph node metastasis, and distant metastasis." (PMID 36277982, 2022).
adenoma (16 papers, 2007 to 2025). A neoplasm arising from the epithelium. "Mouse models have also provided information that loss of Cdx2 expression can influence not only the serrated pathway, but also the classical adenoma–carcinoma pathway." (PMID 31739541, 2019). "CDX2 has on the one hand been described as a tumor suppressor and its loss is associated with development of adenomas in mice." (PMID 30257705, 2018). "CDX2- and CDX2++ proteomes both clustered by replicates of the same patient and importantly also by outcome, suggesting the existence of protein signatures associated with the adenoma to carcinoma transition." (PMID 39252972, 2024). "Previous studies reported that CDX2 loss could be observed at the invasive front, while we detected CDX2 loss not only at the invasive front but also in the adenoma induced by AOM/DSS in mice (red arrow)." (PMID 26910375, 2016). "Given our observation that CDX2++ cells most directly reflect the progression from adenoma to cancer, we evaluated the relative abundance of candidate proteins MARCKS, CD99, and DMBT1." (PMID 39252972, 2024). "To assess the pattern of CDX2 expression during LIN28B-mediated tumorigenesis, we investigated the expression of CDX2 in adenomas in Vil-Lin28b mice by IHC staining." (PMID 33755595, 2021). "Immunohistochemical analysis of adenomas from CDX2;APC mice showed that these lesions were highly proliferative, as characterized by Histone H3-positive cells, while adenomas from CDX2;APC;PID mice had lower levels of Histone H3-positive cells." (PMID 30150766, 2018). "In fact, human serrated adenomas with high-grade dysplasia have been shown to have significantly greater frequencies of CDX2 hypermethylation than other polyp types (like classical adenomas)." (PMID 30257705, 2018). "To address the molecular mechanisms by which the PID repressed proliferation and tumorigenesis in mice, we established 6 primary colonic cell lines from adenomas from both cohorts (CDX2;APC;PID and CDX2;APC, 3 cell lines for each genotype)." (PMID 30150766, 2018). "Two foveolar-type adenomas showed CDX-2(-), MUC5AC(+), MUC6(-), and 2 pyloric gland adenomas showed CDX-2(-), MUC5AC(-), MUC6(+)." (PMID 28467793, 2017). "To clarify what types of adenomas are associated with GDM, we performed IHC for CDX-2 (a marker of intestinal origin), MUC5AC (a marker of gastric foveolar mucin), and MUC6 (a marker of gastric pyloric gland mucin)." (PMID 28467793, 2017). "The other 21 adenomasshowed nuclear β-catenin expression and these were all intestinal-type adenomas identified with expressions of CDX2(+), MUC5AC(-), and MUC6(-)." (PMID 28467793, 2017). "In CAD patients, three patients with severe dysplasia who had two, five and eight CDX2 pCTCs, respectively, before endoscopy showed no CDX2 pCTCs after endoscopy, which suggests that the origin of those CDX2 pCTCs is the adenoma lesion." (PMID 21364588, 2011). "Interestingly, the number of adenomas was 40 and 65% less in small and large intestine in CDX2;APC;PID mice, respectively." (PMID 30150766, 2018). "Dhir and colleagues report that CDX2 is lost in high-grade dysplastic areas of sessile serrated adenomas and may occur due to promoter hypermethylation, an observation that is directly in line with our hypothesis in cancers." (PMID 30257705, 2018). "Loss of epithelial markers, such as CK20, CDX2 and E-cadherin was observed in RCTs but neither in the matched normal mucosa nor adenomas." (PMID 23425390, 2013). "Loss of epithelial markers, (CK20, CDX2 and E-cadherin) and intense vimentin expression was observed in RCTs but neither in the normal mucosa or adenomas." (PMID 23425390, 2013). "More recently, it was reported that the tumor-promoting effect of Cdx2 deficiency on the classical adenoma–carcinoma pathway may be non-cell autonomous." (PMID 31739541, 2019).
adenoma (continued). "Specifically focusing on CDX2++ epithelial cells within high dysplasia regions, we suggest MARCKS, CD99, and DMBT1 as potential indicators for the transition from adenoma to carcinoma." (PMID 39252972, 2024). "In addition to our proposed markers, KRT1, KRT2, and KRT10 were enriched in the C group among the stromal CDX2- population in our previous DVP experiment, consistent with the intensity increase observed in our larger adenoma cohort." (PMID 39252972, 2024). "In contrast, typical adenoma cells produced in elderly APCMin-Villin-GFP mice displayed the opposite expression pattern, being positive for AB-PAS staining, exhibiting high levels of Sox9 expression, and reduced CDX2 expression." (PMID 37923722, 2023). "The Cdx2-negative cells were not contributing to the adenoma, but instead created an environment that promoted neoplasia of Cdx2-positive cells—i.e., Cdx2 was acting as a “non-cell-autonomous tumor suppressor”." (PMID 31739541, 2019). "In addition, strong activation of Pak and Akt was observed in adenomas from CDX2;APC mice, compared to weak staining exhibited in adenomas from CDX2;APC;PID mice." (PMID 30150766, 2018). "A recent study reported CDX2 as a transcriptional repressor of IGFBP-3, accordingly, it is possible that CDX2 and other factors interact with IGFBP-3 in the colon to promote adenoma development." (PMID 18498652, 2008). "To determine if protein patterns specific to CDX2- stromal and CDX2++ epithelial cells could be replicated using alternative methods, we orthogonally investigated DMBT1, CD99, and MARCKS as potential markers for adenoma stratification." (PMID 39252972, 2024). "Interestingly, Bmi1 expression was not apparent in adenomas from either group of animals, whereas patches of strong immunoreactivity were found in infiltrating cells from CDX2;APC mice." (PMID 30150766, 2018).